CNTROB (centrobin, centriole duplication and spindle assembly protein)
Description:
Required for centriole duplication. Inhibition of centriole duplication leading to defects in cytokinesis.
Synonyms: LIP8; PP1221
Tractability: PROTAC: ubiquitination databases record sites on it; its protein half-life has been measured.
Gene: Protein-coding gene on chromosome 17 (7,932,101 to 7,949,920, forward strand). Ensembl gene ENSG00000170037.
Subcellular location: Cytoplasm, cytoskeleton, microtubule organizing center, centrosome, centriole
Subcellular location (Human Protein Atlas): Basal body; Centrosome; Flagellar centriole; Cytosol
Gene Ontology:
Molecular function: protein binding; protein domain specific binding
Biological process: centriole replication; centrosome separation; mitotic cytokinetic process; regulation of cilium assembly
Cellular component: centriole; centrosome; ciliary basal body
Genetic constraint (gnomAD): Loss-of-function variants: 74 observed, 102.1 expected, observed/expected ratio (o/e) 0.72, 90% interval 0.6 to 0.88. The upper end of that interval is the gene's LOEUF score, 0.88, which puts it in group 3 of 6, group 1 being the genes least tolerant of losing a copy. Missense variants: 900 observed, 1,056.7 expected, observed/expected ratio (o/e) 0.85, 90% interval 0.81 to 0.9. Synonymous variants: 386 observed, 428.39 expected, observed/expected ratio (o/e) 0.9, 90% interval 0.83 to 0.98.
Homologues: Orthologues: chimpanzee CNTROB (99% identical), macaque CNTROB (97% identical), pig CNTROB (88% identical), rabbit CNTROB (86% identical), guinea pig CNTROB (85% identical), rat Cntrob (85% identical), dog CNTROB (84% identical), mouse Cntrob (84% identical), tropical clawed frog cntrob (33% identical).
Diseases named in the same sentence as CNTROB in open-access papers:
CNTROB is named in the same sentence as 2 diseases in open-access papers, as found by Europe PMC text mining. Sharing a sentence is not in itself a finding about the gene and the disease.
CNTROB shares sentences with these, for which no sentence is quoted: tumor (2 papers); glioma (1).